RAP1B (RAP1B, member of RAS oncogene family)
Description:
GTP-binding protein that possesses intrinsic GTPase activity. Contributes to the polarizing activity of KRIT1 and CDH5 in the establishment and maintenance of correct endothelial cell polarity and vascular lumen. Required for the localization of phosphorylated PRKCZ, PARD3 and TIAM1 to the cell junction. Plays a role in the establishment of basal endothelial barrier function.
Synonyms: K-REV; RAL1B; DKFZp586H0723; THC11
Tractability: Small molecule: a structure with a bound ligand is known. Antibody: UniProt places it where antibodies can reach, with high confidence; its Gene Ontology location is reachable by antibodies, with high confidence. PROTAC: ubiquitination databases record sites on it; its protein half-life has been measured.
Gene: Protein-coding gene on chromosome 12 (68,610,410 to 68,671,901, forward strand). Ensembl gene ENSG00000127314.
Subcellular location: Cell membrane; Cytoplasm, cytosol; Cell junction
Pathways (Reactome):
Disease: Paradoxical activation of RAF signaling by kinase inactive BRAF; Signaling by BRAF and RAF1 fusions; Signaling by RAF1 mutants; Signaling by high-kinase activity BRAF mutants; Signaling by moderate kinase activity BRAF mutants; Signaling downstream of RAS mutants
Signal Transduction: GRB2:SOS provides linkage to MAPK signaling for Integrins; Integrin signaling; MAP2K and MAPK activation; MET activates RAP1 and RAC1; p130Cas linkage to MAPK signaling for integrins
Immune System: Gene and protein expression by JAK-STAT signaling after Interleukin-12 stimulation; Neutrophil degranulation; Rap1 signalling
Gene Ontology:
Molecular function: GDP binding; GTP binding; GTPase activity; protein binding; protein-containing complex binding; G protein activity
Biological process: cellular response to cAMP; establishment of endothelial barrier; positive regulation of integrin activation; Rap protein signal transduction; regulation of cell junction assembly; regulation of establishment of cell polarity; negative regulation of synaptic vesicle exocytosis; adenylate cyclase-activating G protein-coupled receptor signaling pathway; modification of postsynaptic structure; signal transduction
Cellular component: anchoring junction; cell-cell junction; cytosol; extracellular exosome; lipid droplet; membrane raft; plasma membrane; azurophil granule membrane; membrane; dense core granule; glutamatergic synapse
Genetic constraint (gnomAD): Loss-of-function variants: 0 observed, 16.17 expected, observed/expected ratio (o/e) 0, 90% interval 0 to 0.19. The upper end of that interval is the gene's LOEUF score, 0.19, which puts it in group 1 of 6, group 1 being the genes least tolerant of losing a copy. Missense variants: 64 observed, 159.59 expected, observed/expected ratio (o/e) 0.4, 90% interval 0.33 to 0.49. Synonymous variants: 59 observed, 57.35 expected, observed/expected ratio (o/e) 1.03, 90% interval 0.83 to 1.28.
Gene-disease validity (ClinGen):
ClinGen rates the evidence that RAP1B causes each of these diseases.
thrombocytopenia 11 with multiple congenital anomalies and dysmorphic facies (autosomal dominant): Moderate.
Homologues: Orthologues: chimpanzee RAP1B (100% identical), guinea pig RAP1B (100% identical), macaque RAP1B (100% identical), mouse Rap1b (100% identical), pig RAP1B (100% identical), dog RAP1B (99% identical), rat Rap1b (99% identical), tropical clawed frog rap1b (98% identical), zebrafish rap1b (96% identical). Paralogues in human: RAP1A (95% identical), RAP2A (61% identical), RAP2B (61% identical), RAP2C (60% identical), HRAS (53% identical), KRAS (53% identical), RRAS (53% identical), RRAS2 (53% identical), NRAS (52% identical), MRAS (51% identical), RALA (49% identical), RIT1 (48% identical), and 23 more.
Diseases named in the same sentence as RAP1B in open-access papers:
RAP1B is named in the same sentence as 88 diseases in open-access papers, as found by Europe PMC text mining. Sharing a sentence is not in itself a finding about the gene and the disease. The quoted sentences say what the papers report.
ovarian carcinoma (11 papers, 2014 to 2024). A malignant neoplasm originating from the surface ovarian epithelium. "In addition, SNORA70E binds DKC1 to regulate Ras‐associated protein 1B (RAP1B) mRNA and increase RAP1B protein level through pseudouridine modification, thereby promoting cancer cell progression in ovarian cancer." (PMID 38572667, 2024). "Furthermore, clinical data reveal that low miR-708 and high Rap1B levels are associated with advanced-stage ovarian cancer, and high miR-708 predicts significantly better survival." (PMID 25569036, 2015). "PTX-resistant ovarian cancer tissues and cells had an upregulation of circ_0000231 and RAP1B and a downregulation of miR-140 level." (PMID 38152652, 2023). "The downregulation of miR-708 in ovarian cancer cells resulted in the suppression of Rap1b, thereby impairing integrin-mediated cellular junction formation, migration, and invasion." (PMID 36101746, 2022). "In conclusion, SNORA70E promotes the occurrence and development of ovarian cancer through pseudouridylation modification of RAP1B and alternative splicing of PARPBP." (PMID 36056690, 2022). "Hsa-miR-708 acts as an oncogene in lung cancer by downregulating TMEM88, but was reported to suppress ovarian cancer metastasis through targeting Rap1B." (PMID 29755664, 2018). "Restoring Rap1B expression reverts glucocorticoid-miR-708 cascade-mediated suppression of ovarian cancer cell invasion and metastasis." (PMID 25569036, 2015). "We propose that miRNA-708-mediated suppression of Rap1B plays an important role in inhibiting ovarian cancer cell migration/invasion and metastasis." (PMID 25569036, 2015). "Overall, we demonstrate for the first time that GC-mediated signalling inhibits ovarian cancer abdominal metastasis, and expression of Rap1B significantly restored metastasis from this inhibition." (PMID 25569036, 2015). "Here our data showed that suppression of Rap1B by miR-708 resulted in the decreased migration/invasion of ovarian cancer cells." (PMID 25569036, 2015). "Overall, our results indicate that Rap1B is functionally important for miR-708-mediated regulation of ovarian cancer cell migration/invasion." (PMID 25569036, 2015). "Expression of miR-708 results in decreased ovarian cancer cell migration/invasion and metastasis mainly through targeting Rap1B." (PMID 25569036, 2015). "In order to evaluate the clinical relevance of Rap1B in ovarian cancer progression, we analysed its expression in commercial cDNA arrays and frozen tissues obtained from Taipei Veterans General Hospital (TVGH)." (PMID 25569036, 2015). "Signalling mediated by GCs induced miR-708 expression, leading to the suppression of Rap1B, the impairment of integrin-mediated FA formation, and suppression of ovarian cancer metastasis." (PMID 25569036, 2015). "Further, miR-140 can be sponged by circ_0000231, and target RAP1B in ovarian cancer." (PMID 38152652, 2023). "Glucocorticoid treatments induce the expression of miR-708, leading to the suppression of Rap1B, which result in the reduction of integrin-mediated focal adhesion formation, inhibition of ovarian cancer cell migration/invasion and impaired abdominal metastasis in an orthotopic xenograft mouse model." (PMID 25569036, 2015). "The function of Rap1B and Rap1A in ovarian cancer migration/invasion was then tested." (PMID 25569036, 2015). "The Rap1B inhibition by miR-708 was also observed in other ovarian cancer cell lines." (PMID 25569036, 2015). "In this study, we have identified the involvement of Rap1B in ovarian cancer metastasis." (PMID 25569036, 2015). "Although our data only reflected mRNA levels, and some genes might be affected translationally, we decided to focus on Rap1B as the major target of miR-708 in ovarian cancer." (PMID 25569036, 2015). "The treatment of C57BL/6-derived ovarian cancer ID-8 cells with a synthetic GC, dexamethasone (DEX), induced the expression of microRNA-708, leading to decreased cell migration and invasion through targeting Rap1B." (PMID 28591224, 2017).
ovarian carcinoma (continued). "Furthermore, with respect to the distinct isoforms, Rap1A and Rap1B, our data revealed that only depletion of Rap1B, but not Rap1A, significantly inhibited migration/invasion of ovarian cancer cells, suggesting the dominant role of Rap1B in promoting migration/invasion." (PMID 25569036, 2015).
glioma (10 papers, 2019 to 2025). A benign or malignant brain and spinal cord tumor that arises from glial cells (astrocytes, oligodendrocytes, ependymal cells). "In addition, numerous studies have reported that CCND1/RAP1B is associated with glioma cell proliferation and invasion." (PMID 33676540, 2021). "To further explore the association between miR-28-5p and Rap1b in glioma cells, we analyzed the expression of the endogenous Rap1b after transiently transfecting cells with either (a) miR-28-5p mimics, (b) miR-28-5p inhibitor, or (c) control miR-28-5p-NC in A172, U87MG, U373MG, and SNB19 cells." (PMID 31921670, 2019). "Silencing of MALAT1 in glioma cell lines reduced proliferation and enhanced apoptosis, while suppression of miR-101 or over-expression of Rap1B had the opposite effects on proliferation and apoptosis." (PMID 35071748, 2022). "Consistent with our findings, studies have shown that abnormal miRNA expression can affect gliomas by targeting RAP1B." (PMID 33676540, 2021). "According to the expression in glioma and adjacent tissues in GEPIA, only RAP1B was highly expressed in gliomas, which was chosen for following study." (PMID 33676540, 2021). "For instance, lnc MALAT1 has been reported to promote proliferation and inhibit apoptosis through derepressing Rap1B by sponging miR-101 in glioma cells, while it is also confirmed to inhibit breast cancer metastasis as a metastasis suppressor." (PMID 32735016, 2020). "Taken together, these results suggest that Rap1b increases glioma cell line proliferation and invasion, and promotes glioma tumorigenesis and metastasis." (PMID 31921670, 2019). "In this study, we found Rap1b demonstrated the mitogenic roles in both glioma cell proliferation and invasion." (PMID 31921670, 2019). "Our results showed that miR-28-5p inhibits glioma cell proliferation and invasion by targeting its downstream Rap1b gene, and miR-28-5p is regulated by TRPM7." (PMID 31921670, 2019). "TRPM7 regulates miR-28-5p expression, which suppresses cell proliferation and invasion in glioma cells by targeting Rap1b signaling." (PMID 31921670, 2019). "Rap1b mRNA expression levels were significantly reduced by miR-28-5p mimics and significantly enhanced by miR-28-5p inhibitor in each of the four glioma cell lines." (PMID 31921670, 2019). "MALAT1 promotes the expression of sex determining region Y-box 2 (SOX2), thus boosting the viability and proliferation of glioblastoma stem cells, and it also suppresses apoptosis of glioma cells through reduction of Ras-related protein Rap-1b (Rap1B) levels by removal of miR-101." (PMID 32650527, 2020). "As expected, the reduction of Rap1b expression by siRap1b effectively reduced glioma cell proliferation induced by miR-28-5p inhibitor during 24 to 96 h post-transfection by a maximum of 52, 41.8, and 69.2% for A172, U87MG, and U373MG at 96 h, 60% for SNB19 at 48 h." (PMID 31921670, 2019). "miR-28-5p suppressed glioma cell proliferation and migration by targeting Rap1b." (PMID 31921670, 2019). "Lastly, we determined whether a Ras-related small GTP-binding protein (Rap1b) is a target of miR-28-5p in glioma tumorigenesis." (PMID 31921670, 2019). "First, Rap1b has been found to play a role in the glioma cell proliferation and migration." (PMID 31921670, 2019). "Moreover, miR-28-5p induced apoptosis of chronic lymphocyte leukemia cells and hindered the proliferation and migration of glioma cells by targeting Rap1b and interfering with genes involved in cell replication and cell cycle checkpoint, whose results were consistent with our previous research." (PMID 35873635, 2022). "We wondered whether CCND1 and RAP1B could affect the PI3K/AKT/mTOR signaling pathway in glioma." (PMID 33676540, 2021). "In this study, they measured the expression levels of miR-101, Rap1B mRNA, and MALAT1 in U87 and U251 glioma cells." (PMID 35071748, 2022). "As shown by Western blot, all of the glioma cell lines A172, SF767, SNB19, U373MG, and U87MG expressed the Rap1b protein." (PMID 31921670, 2019).
glioma (continued). "Collectively, these results revealed that RAP1B and CCND1 could activate the PI3K/AKT/mTOR signaling pathway in glioma cells." (PMID 33676540, 2021). "To sum up, we unearthed that M2 macrophage-derived miR-15a and miR-92a could target CCND1 and RAP1B, respectively, thereby inhibiting the invasion and migration via blocking PI3k/AKT/mTOR signaling pathway in gliomas." (PMID 33676540, 2021). "We first determined whether or not Rap1b protein, a Ras-related small GTP-binding protein that acts as GTPase in several signaling cascades, is expressed in glioma cells." (PMID 31921670, 2019).
colorectal cancer (8 papers, 2017 to 2024). A primary or metastatic malignant neoplasm that affects the colon or rectum. "miR-30b-5p can also inhibit EMT by targeting Rap1b, thereby suppressing colorectal cancer metastasis." (PMID 38796629, 2024). "In several types of tumors, such as colorectal cancer, renal cell carcinoma, and melanoma, reducing the expression of RAP1B effectively inhibits tumor cell proliferation and migration 73-75." (PMID 37576389, 2023). "In colorectal cancer cells, RAP1B was found to be a direct and functional target of miR-30b-5p to regulate cell adhesion and mobility." (PMID 33261656, 2020). "MiR-139 regulated human colorectal carcinoma cell proliferation by targeting RAP1B accompanied by a large change in the phosphorylation level of p38." (PMID 30460078, 2017). "Furthermore, the tumor suppressor effect of RAP1B on OC is consistent with its role in other cancers such as thyroid cancer and colorectal cancer." (PMID 36277988, 2022). "However, two recent papers showed that miR-100 and miR-139 strongly decreased colorectal carcinoma cell proliferation by directly targeting RAP1B." (PMID 29657291, 2017). "The role of RAP1B in cancer is not entirely clear, but some miRNAs that target RAP1B have been found to inhibit cell migration, invasion, and metastasis in various types of tumors, such as miR-100 in colorectal cancer or miR-149 in lung adenocarcinoma." (PMID 35632705, 2022).
renal cell carcinoma (8 papers, 2016 to 2023). "A study reported that miR-28-5p inhibited cell proliferation and migration by directly suppressing Rap1b gene in renal cell carcinoma." (PMID 31921670, 2019). "The most related pathway to SOX2OT inhibition was renal cell carcinoma (Kegg: 05211, corrected p value = 0.004953) with 5 genes differentially expressed in RNA sequences of both cells (hif1a, hras, pik3ca, rap1b, vhl)." (PMID 30202240, 2018). "In particular, it has been demonstrated that miR-28-5p suppressed cell proliferation and migration by directly inhibiting RAP1B in renal cell carcinoma." (PMID 29085832, 2017). "Additionally, miR-28-5p inhibited cell proliferation and migration in Renal Cell Carcinoma by directly inhibiting the Rap1b gene." (PMID 35873635, 2022). "In addition, miR-28-5p acted as a TS-miRNA in renal cell carcinoma by directly repressing the expression of RAP1B and in B-cell lymphoma by directly inhibiting BAG1 expression, a gene involved in the MAP-kinase pathway regulation." (PMID 29085832, 2017). "The expression of hsa-miR-28-5p inhibits the proliferation of B-cell lymphoma and renal cell carcinoma cells by regulating the expression of BAG1 and RAP1B, respectively." (PMID 35027933, 2022). "By inhibiting the expression of Rap1b, the proliferation and migration of hepatocellular carcinoma (HCC), renal cell carcinoma (RCC), esophageal squamous cell carcinoma (ESCC), colorectal cancer cells (CRC) and melanoma cells had been inhibited." (PMID 34346294, 2021).
thyroid cancer (8 papers, 2020 to 2022). "In thyroid cancer cells, miR-200b/c inhibits the activity of the NF-κB/Twist-1 pathway and suppresses cell migration and invasion by reducing RAP1B levels." (PMID 35632705, 2022). "According to relevant literature, miRNAs in the ceRNA network is involved in the regulation of cancer occurrence and development, such as miR-206 can inhibit the proliferation and invasion of thyroid cancer by targeting RAP1B." (PMID 35913967, 2022). "For instance, miR-206 hampered the proliferation and invasion of thyroid cancer cells through targeting RAP1B." (PMID 33526034, 2021). "The previous study suggested downregulation of Ras-related protein Rap-1b could effectively inhibit the tumorigenesis of thyroid cancer cells." (PMID 35360110, 2022).
glioblastoma (7 papers, 2012 to 2022). The most malignant astrocytic tumor (WHO grade IV). "Upregulation of miR-128 inhibited glioblastoma invasion and dissemination by targeting Rap1B-mediated cytoskeletal remodeling and related substances, including N-cadherin, cell division cycle 42 (Cdc42), and RhoA." (PMID 36793341, 2022). "Rap1a and Rap1b are 95% homologous, but differences in subcellular localization of two isoforms and their mechanisms of activation resulted in their distinctive functions and roles in glioblastoma cell proliferation." (PMID 31921670, 2019). "Furthermore, miR-149 is also downregulated in glioblastoma cells and has been proposed to act as a tumor suppressor by targeting RAP1B, CD47, CCN1, and NXF1." (PMID 23144691, 2012). "Interestingly, miR-125b inhibitor boosts the chemosensitivity of glioblastoma stem cells to TMZ by targeting Bak1, whereas the miR-128, miR-149 and miR-181 families enhance the chemosensitivity of glioblastoma cells to TMZ by targeting Rap1B." (PMID 25605243, 2015).
breast carcinoma (6 papers, 2017 to 2024). "Interestingly, also downregulated in ADCs was miR-149, which was demonstrated previously to have tumor suppressor capacity in breast cancer migration and invasion by targeting small GTPases Rap1a and Rap1b." (PMID 28787442, 2017). "The members of the miR-23a ~ 27a ~ 24-2 cluster integrally inhibit the aggressiveness of breast cancer cells by targeting NCOA1, NLK, and RAP1B." (PMID 39112518, 2024). "Few targets of miR-708 have been proven to participate in cell motility, including Rap1B in ovarian cancer, KPNA4 in prostate cancer, and NNAT in breast cancer." (PMID 37083947, 2023). "It is possibly dominated by other downstream targets mediated by miR-708, for example, Rap1B and NNAT in ovarian and breast cancer." (PMID 37083947, 2023).
gastric cancer (6 papers, 2019 to 2025). A primary or metastatic malignant neoplasm involving the stomach. "It was found that RAP1B was associated with poor prognosis and promoted an aggressive phenotype in gastric cancer." (PMID 40638546, 2025). "The published article titled “Knockdown of Rap1b Enhances Apoptosis and Autophagy in Gastric Cancer Cells via the PI3K/Akt/mTOR Pathway” has been retracted from Oncology Research, Vol." (PMID 40746886, 2025). "This study assessed Nrf2 and HO-1 expression and hypoxia-induced Nrf2 expression in the promotion of metastatic potential of gastric cancer cells, the relationship of Rap1b and Nrf2 was also discussed." (PMID 35417854, 2022). "It is the first study that clarify that FN1 could suppress the binding of RAP1B to PARK2 to stabilise RAP1B protein, thereby activating Akt signalling pathway and promoting gastric cancer migration and metastasis." (PMID 40638546, 2025). "Hypoxia promoted the gastric cancer malignant behavior through the upregulation of Rap1b and Nrf2." (PMID 35417854, 2022). "Targeting Rap1b and Nrf2 may be a novel therapeutic strategy for gastric cancer." (PMID 35417854, 2022). "Overexpression of FN1 promoted gastric cancer migration, invasion, EMT, and metastasis via RAP1B in vitro and in vivo." (PMID 40638546, 2025).